IL17A (interleukin 17A)
Diseases named in the same sentence as IL17A in open-access papers (continued):
Sharing a sentence is not in itself a finding about the gene and the disease.
tumor (continued). "The effect of IL-17A on tumor growth was confirmed by treating tumors with IL-17A antibody, which abolished the acceleration of tumor growth." (PMID 25181290, 2014). "To determine if treatment reduced IL-17A levels within the tumor and metastatic niches, we evaluated the levels of IL-17A using an ELISA." (PMID 24674692, 2014). "Interleukin 17A (IL-17A), as a pro-inflammatory cytokine, is involved in pathology of inflammatory diseases and tumor microenvironment." (PMID 24905806, 2014). "When tumor cells were inoculated into irradiated tumor beds, the tumor growth rate and IL-17A expression drastically were increased relative to the controls." (PMID 25181290, 2014). "Allograft tumor growth was slower in Il17a−/−, Il1r1−/−, Nlrp3−/−, and Casp1−/− mice after chemotherapy treatment, demonstrating all elements in this pathway play a part in tumor protection although the exact mechanism is unclear." (PMID 24795727, 2014). "Collectively, these data suggest that IL-17A-producing T cells promote tumor progression via multiple mechanisms." (PMID 24987392, 2014). "Data clearly suggests that when SKG mice were induced to develop tumors, the level of SDF-1 significantly increased in the lungs and that treatment with anti-IL-17A antibody brought the levels back down to the non-tumor bearing levels." (PMID 24674692, 2014). "In conclusion, the results of our study suggest that low-dose irradiation of tumor beds can induce IL-17A production via IL-6 and TGF-β production, and promote the growth of subsequently implanted tumors." (PMID 25181290, 2014). "In contrast, other studies suggested that IL-17A showed a protective effect against chronic lymphocytic leukemia development by promoting immune system-mediated tumor rejection." (PMID 24905806, 2014). "In HCa-I, tumor growth in the pre-irradiated beds was faster in the pre-5 Gy/D1 and D3 groups than in the control group, and was correlated with IL-17A production." (PMID 25181290, 2014). "Pro-inflammatory cytokines secreted by Th17 cells, such as IL-17A, impair immune surveillance and promote tumor growth." (PMID 24987392, 2014). "Using animal model, some studies find that IL-17A inhibited tumor growth and metastasis through IFN-c producing NK and T cells." (PMID 25250801, 2014). "This takes place in response to the release of lactate from the tumour cells resulting in increased release of IL-17, in particular IL-17A, via IL-23 dependent and independent pathways." (PMID 25110397, 2014). "IL-17A is one of the important inflammatory cytokines in the development of many inflammatory diseases and is also frequently detected in tumor microenvironment." (PMID 24905806, 2014). "Among the cytokines secreted by Th17 cells, IL-17A is best known to induce angiogenesis in tumor tissue." (PMID 24987392, 2014). "In this study, tumor growth was suppressed by IL-17A neutralization; however, growth was still slightly faster than that in the non-irradiated control." (PMID 25181290, 2014). "Compared to the control group, the level of IL-17A in the tumor of SKG mice treated with anti-IL-17A antibody was significantly lower." (PMID 24674692, 2014). "IL-6 promotes the differentiation of Th17 cells, and IL-17A also amplifies IL-6 production in the tumor." (PMID 23372655, 2013). "To examine why CTL activity, especially in the tumor microenvironment, was enhanced by inhibiting IL-17A in tumor tissues, we examined the Th1/Th2 phenotype of T lymphocytes of spleen cells and TILs in the MC38 subcutaneous model." (PMID 23372655, 2013). "Subsequently, IL-17−/− mice have been used to determine the endogenous IL-17A functions with regard to tumor progression." (PMID 23372655, 2013). "Although these studies seem to suggest that the compete elimination of IL-17A favor the migration of CD8+ T cells to tumor sites leading to augmentation of antitumor immunity, the cytotoxic activity of TILs is not fully understood." (PMID 23372655, 2013).
tumor (continued). "One report using B16 melanoma cell lines showed that IL-17A promoted tumor growth via angiogenesis and induced IL-6 production, which in turn activated oncogenic Stat-3, up-regulating prosurvival and proangiogenic genes." (PMID 23372655, 2013). "In fact, in the present study, inhibiting of IL-17A at tumor sites decreased IL-6 and CCL2 in tumors, and the migration of MDSCs in tumor tissues was obviously reduced." (PMID 23372655, 2013). "By contrast, in hematopoietic tumors such as mastocytoma or plasmacytoma, IL-17A prevented tumor development by increasing the generation of tumor specific cytotoxic T lymphocytes." (PMID 23441221, 2013). "Next, to investigate the mechanism by which Th1 cells and CTLs were activated though inhibition of IL-17A in the tumor microenvironment, we assessed immunosuppressor cells, such as MDSCs and Treg cells, in splenocytes or TILs." (PMID 23372655, 2013). "Several studies have suggested pro-tumor effect of Th17 cells or IL-17A in hepatic tumor formation and progression, shortening patient survival by promoting tumor angiogenesis." (PMID 24069246, 2013). "In vivo the microvessel density in tumor tissues is increased by overexpression of IL-17A at tumor sites and decreased in IL-17−/− mice." (PMID 23372655, 2013). "In conclusion, blockade of IL-17A at tumor sites helped suppress tumor growth by inhibiting angiogenesis as well as cytotoxic T lymphocytes activation at tumor sites." (PMID 23372655, 2013). "We first examined how inhibiting locally expressed IL-17A affected tumor growth by using a B16 subcutaneous tumor model." (PMID 23372655, 2013). "Most recently, it has been reported that IL-17A promotes the infiltration of MDSCs at tumor sites and augments the development and function of MDSCs." (PMID 23372655, 2013). "In mice, overexpression of IL-17A by gene transduction into tumor cells promoted tumor growth through angiogenesis, but seemingly in contrast, IL-17A also suppressed tumor growth via a T-cell dependent mechanism." (PMID 23372655, 2013). "The overexpression of IL-17A at tumor sites suppressed tumor progression through the enhanced tumor-specific CTL response in immunocompetent mice." (PMID 23372655, 2013). "Next, to investigate the mechanisms of tumor growth suppression by IL-17A inhibition, we performed immunohistochemistry of tumor tissues with regard to angiogenesis." (PMID 23372655, 2013). "To investigate the effect of the inhibition of IL-17A in tumor tissue on systemic and local anti-tumor immunity, we assessed the cytotoxic activity of CD8+ T cells from splenocytes or TILs in the MC38 subcutaneous model." (PMID 23372655, 2013). "In the present study, we clearly showed that inhibition of naturally expressed IL-17A at tumor sites suppressed tumor growth." (PMID 23372655, 2013). "In the present study, we showed that cytotoxicity of CD8+ T cells from TILs was activated by inhibiting IL-17A at tumor sites, and in contrast, the cytotoxicity of CD8+ T cells from spleen cells was not affected." (PMID 23372655, 2013). "We investigated the effect of inhibiting IL-17A at tumor sites on tumor growth and on local and systemic anti-tumor immunity." (PMID 23372655, 2013). "MC38 or B16 cells were inoculated subcutaneously into mice, and intratumoral injection of an adenovirus vector expressing siRNA against the mouse IL-17A gene (Ad-si-IL-17) significantly inhibited tumor growth in both tumor models compared with control mice." (PMID 23372655, 2013). "In mouse models of fibrosarcoma or colon adenocarcinoma, over-expression of IL-17A by cancer cells increased tumor growth." (PMID 23441221, 2013). "Some studies showed IL-17A supports tumor growth by facilitating angiogenesis of cervical cancer and lung cancer." (PMID 22509371, 2012). "Analysis of mechanisms underlying this effect revealed that IL-21 sustains CD4+ T cell infiltration in the tumor and peritumor areas and enhances the production of IL-6 and IL-17A as well as STAT3 activation." (PMID 23109839, 2012).
tumor (continued). "As a conclusion these findings strongly support the idea that IL-17A is involved in tumor growth promotion." (PMID 22855687, 2012). "IL-17A has been found in various tumors and appears to have both pro-tumor and anti-tumor roles depending on the type of tumors and also the existence of host lymphoid system." (PMID 22509371, 2012). "The changes of Th17 cells along disease progression were accompanied by alterations of IL-1β, IL-6, IL-17A, IL-23 in serum and IL-1β, IL-6 in tumor tissues." (PMID 22994684, 2012). "In contrast, other reports suggested IL-17A promotes T cell-mediated tumor rejection in fibrosarcoma, hematopoietic immunogenic tumor and lung melanoma." (PMID 22509371, 2012). "One explanation for the putative, tumor-promoting function of IL-17A is that the expression and the function of this cytokine are closely related to the proto-oncogene Stat3." (PMID 22855687, 2012). "One possible explanation is that another cell in the tumor microenvironments was regulated by IL-17F/IL-17A in production of VEGF." (PMID 22509371, 2012). "IL-17A is a pro-inflammatory cytokine that plays important role in inflammatory disease pathology and tumor microenvironment." (PMID 21760911, 2011). "In the present study, higher frequency of IL-17A positive cells in tumor tissue was significantly associated with poorer prognosis of HCC (P = 0.01) by promoting HCC metastasis, suggesting that IL-17A played an important role in promoting HCC progression." (PMID 21760911, 2011). "Transcript levels of MMP2, MMP9 and IL-17A were measured in another 50 pairs (including tumor and related non-tumor tissues) HCC samples." (PMID 21760911, 2011). "IL-21 mRNA was expressed concomitantly with IL-17 mRNA in tumor-bearing eyes and intracellular expression of IL-17A and IL-21 in infiltrating CD4+ T lymphocytes." (PMID 21949734, 2011). "IL-17A is an important inflammatory cytokines in the development of many inflammatory diseases and it is also frequently detected in tumor microenvironment." (PMID 21760911, 2011). "The frequency of IL-17A-positive cells in tumor tissues was significantly higher in HCC cases with metastasis than that without metastasis (P = 0.002, Independent sample T test)." (PMID 21760911, 2011). "While other studies show that IL-17A can promote tumor growth and metastasis through IL-6/Stat3 signaling pathway or through the induction of tumor promoting microenvironment at tumor site." (PMID 21760911, 2011). "Using animal model, some studies find that IL-17A can inhibit tumor growth and metastasis through IFN-γ producing NK and T cells." (PMID 21760911, 2011). "IL-17B does not exert strong proinflammatory effects associated with IL-17A and is thought to contribute significantly to embryonic formation, tissue restoration, and tumor advancement." (PMID 40536951, 2026). "In summary, the analysis suggests a weak but statistically suggestive association between IL-17A and IL-8 concentrations, with no meaningful contribution from tumor grade." (PMID 40725273, 2025). "Importantly, a multivariate model including IL-8, IL-17A, IL-33, and tumor grade accounted for over 70% of the variance in IL-17A expression, reinforcing the complex interplay among these cytokines in shaping the tumor microenvironment." (PMID 40725273, 2025). "Second, antibodies or small molecule inhibitors targeting IL-17A and IL-26 secreted by Tc17 cells may effectively block their tumor-promoting actions." (PMID 40452847, 2025). "Likewise, 17-type polarized ILC subtypes secrete IL-17A, which contribute to metastasis by facilitating angiogenesis through the stroma or stimulate tumor cells proliferation directly." (PMID 40352926, 2025). "The sharp decline in IL-17A concentrations with poorer differentiation may suggest a diminishing role of Th17-related inflammation in more aggressive tumor phenotypes." (PMID 40725273, 2025).
tumor (continued). "In contrast, IL-17A and IL-33 levels decreased progressively with declining tumor differentiation, which may indicate their involvement in early stage inflammatory signaling and the subsequent suppression of immune responses in more advanced cancer." (PMID 40725273, 2025). "Moreover, Th17 cells secrete cytokines such as IL-17A and IL-22, which contribute to tumor proliferation and immunosuppression." (PMID 41209556, 2025). "IL-17A showed peak expression in submucosal invasion but declined with tumor dedifferentiation and in metastatic stages, indicating a proinflammatory role in early tumor progression that diminishes as immune suppression intensifies." (PMID 40725273, 2025). "Furthermore, OC’s suppression of prostaglandin E2 (PGE2) disrupts Th17 plasticity by blocking cAMP-responsive element modulator (CREM)-α-mediated IL-17A transcription, thereby stabilizing Th1/Th17 ratios in favor of anti-tumor immunity." (PMID 40564985, 2025). "The metastatic niche presentation of SFB epitopes activates tumor-infiltrating Th17 cells strongly, which then initiate a complex anti-tumor cytokine cascade through increased IL-17A and IFN-γ production by CD4+ T cells and CD8+ T cells, and natural killer cells." (PMID 41441899, 2025). "Patient selection could be guided by baseline IL17A levels in serum or tumour, enabling a precision‐medicine approach." (PMID 40831074, 2025). "This dynamic could reflect a regulatory mechanism in the tumor microenvironment, where IL-17A is upregulated under moderate IL-8 levels but potentially suppressed at very high IL-8 concentrations, possibly due to feedback inhibition or immune exhaustion." (PMID 40725273, 2025). "Furthermore, IL-17a also participates in tissue repair and can influence cancer progression by supporting angiogenesis and tumor growth, though context-dependent antitumor roles have also been described." (PMID 41310729, 2025). "The scatterplots showed variability in IL-17A expression across different patterns of tumor invasion, suggesting that specific invasive behaviors may modulate inflammatory cytokine signaling." (PMID 40725273, 2025). "Notably, these tumor-associated MAIT cells exhibit a Th17-skewed functional profile, characterized by an enrichment of IL-17A-producing cells, the MAIT17 subset." (PMID 40746558, 2025). "Conversely, CD300a/c− CD4+ T cells are more related to a TH17 profile, expressing IL-17A, which may promote tumor progression in certain tumor microenvironments." (PMID 40507267, 2025). "Furthermore, CD8+ T cells were significantly more abundant both in vaccinated KPC/IL17A−/− mice and in the orthotopic tumours treated with an anti‐IL17A mAb." (PMID 40831074, 2025). "And in turn, Tc17 cells may promote tumor progression by secreting IL-17A and IL-26, as functionally corroborated by CCK-8 Assay, wound healing, and transwell assay in vitro." (PMID 40452847, 2025). "Both tumor and immune cells showed cytoplasmic staining for IL17A." (PMID 41429763, 2025). "Th17 cells could promote the expansion of regulatory T cells through the release of IL‐17A, facilitating immune evasion by tumor cells." (PMID 40629930, 2025). "Additionally, in the LUAD mice model, IL-17A was demonstrated to promote tumor growth by inducing IL-6." (PMID 41376623, 2025). "In addition, IL-10 and IL-17A, among the top activated pathways, have been shown to have tumor-promoting roles." (PMID 39805854, 2025). "Furthermore, certain antitumor factors, including IL-2, IL-10, and IL-17A, mitigate tumor immune evasion, contributing to improved outcomes." (PMID 40313970, 2025). "Th17 cells, particularly through the secretion of IL-17A, can promote tumor angiogenesis." (PMID 41041322, 2025). "MAIT cells in MM and AML patients highly express inhibitory receptors such as PD‐1 and TIM‐3, and cytokines such as IL‐10 and TGF‐β can weaken their cytokine secretion ability, or even make them switch to a proinflammatory phenotype that secretes IL‐17A, thereby promoting tumor angiogenesis." (PMID 41179703, 2025).
tumor (continued). "Residual killing activity following CD8+ T‐cell depletion in IL17A−/− splenocytes suggested a contributory role of NK cells, which was confirmed by increased tumour growth following NK1.1 cell depletion in IL17A−/− mice, as shown in the representative H&E images." (PMID 40831074, 2025). "In this intricate process, IL-17A has an important role in thwarting tumor immune evasion." (PMID 40313970, 2025). "CD8+ T‐cell depletion increased tumour burden in both IL17A‐proficient and ‐deficient KPC mice (data not shown)." (PMID 40831074, 2025). "IL-17A may directly influence endothelial cells, stimulate tumor growth by enhancing angiogenesis in immunocompetent hosts, or upregulate adhesion molecules and endothelial cell permeability." (PMID 40558272, 2025). "This dual role makes IL-17 a pivotal link between chronic fungal infections and tumor metastasis." (PMID 40557321, 2025). "Notably, the interaction plot between the IL-8 concentration and tumor grade vividly illustrates how IL-17A levels vary by both the magnitude of IL-8 and tumor differentiation, exhibiting quadratic correlations." (PMID 40725273, 2025). "In oral cancer cells, IL-17A induces M2 macrophage polarization to advance tumor development." (PMID 38430256, 2024). "IL-17A could also stimulate unnecessary tumor growth by influencing IL-6, which in turn activates tumorigenic signal transducer and activator of transcription (STAT3) signaling pathway and over-express genes associated with pro-survival and pro-angiogenesis." (PMID 38816694, 2024). "Depletion of Il17a or Il17f reduces tumor development in APC-driven mouse models of CRC." (PMID 38918278, 2024). "This hypothesis is consistent with previous research findings on the role of IL-17A in tumor immunity, but its specific molecular mechanisms still require further experimental validation." (PMID 39257908, 2024). "Th17 cells had reduced IL17a expression and weakened interactions with other cell populations in Cyp51-KO tumors, including the axis of Th17- neutrophils/macrophages and Th17-tumor cells." (PMID 38177537, 2024). "Additionally, more M2-like macrophages accumulated in the tumor of mice with M. globosa infection, and this was reduced after IL-17A neutralization." (PMID 39235230, 2024). "However, γδ T cells can also facilitate the proliferation and migration of NB tumor cells by generating IL-17 and releasing cytokines such as IL-17A." (PMID 39253082, 2024). "Our results may suggest that IL17A+CD4+ T cells associated with PD-L1+ lymphocytes can lead to immunosuppression and a tumour-immune escape acting in tumour islets." (PMID 39409156, 2024). "Interestingly, IL-17A has a dual role in tumor development, whereas IL-17F exhibits tumor-suppressing properties." (PMID 38415252, 2024). "Another good example of neutrophil pro-tumor is via inflammatory factor IL17a." (PMID 38244071, 2024). "Producing γδT cells may produce some specific factors, mainly IL-17A, which may play a pro-tumor role." (PMID 39906741, 2024). "WB results showed that p-p38 and IL-17A expression in tumor tissue was decreased by Oct4 knockdown." (PMID 38430256, 2024). "As an important anti-inflammatory factor, IL-17A may exert its anti-tumor effects by inhibiting the expression of these genes, thereby reducing the levels of oxidative stress and inflammatory responses in the body." (PMID 39257908, 2024). "Similarly, overexpression of IL-17a facilitated liver tumor formation, and the tumor initiation frequency of the IL-17-OE cells was much higher than that of the corresponding control cells." (PMID 38740736, 2024). "Previous studies have shown that ferulic acid and its derivatives can promote tumor cell proliferation, invasion, and metastasis by activating signaling pathways such as MAPK and NF-κB, while IL-17A can inhibit the activity of these tumor-related signaling pathways." (PMID 39257908, 2024).